IL5 (interleukin 5)
Diseases named in the same sentence as IL5 in open-access papers (continued):
Sharing a sentence is not in itself a finding about the gene and the disease.
cardiovascular disease (10 papers, 2016 to 2025). "The majority of the inflammatory proteins that were found to be significantly elevated have been associated with increased cardiovascular disease such as, interleukin-5, cluster of differentiation 40 (CD40) and interleukin-1beta31, whilst FGF8 has been more associated with vascular remodeling." (PMID 32179763, 2020). "Data from both clinical experiments and animal studies have shown that IL‐5 expression is significantly altered in cardiovascular disease." (PMID 38963241, 2024). "While human plasma IL-5 levels do not predict cardiovascular disease risk, elevated IL-5 levels have been linked to reduced carotid intima-media thickness and increased production of oxidized LDL-specific antibodies." (PMID 40566616, 2025). "IL‐5 has also been shown to be involved in a variety of cardiovascular diseases." (PMID 38963241, 2024). "When identifying if there were correlations between the serum markers, a marker of cardiovascular disease, MCP1, generated the most correlative relationships, followed closely by the inflammatory marker IL5." (PMID 38201205, 2023). "Regarding CAD, a study based on biobanks and databases from the IMPROVE study—a prominent European prospective cohort study comprising high-risk individuals who were initially free of clinically overt cardiovascular disease—concluded that IL-5 is not useful as a biomarker for CAD." (PMID 39201047, 2024).
hematologic malignancies (6 papers, 2017 to 2025). "Several hematological malignancies can lead to HE and serve as a cause of secondary HE/HES, characterized by an expansion of the eosinophil lineage due to interleukin (IL)-5 overproduction." (PMID 39056762, 2024). "STAT3, IL5, and TLR4 normalized counts showed similar patterns to NGAL normalized counts in hematological malignancy and control groups." (PMID 34400898, 2021).
gastrointestinal disorders (3 papers, 2014 to 2025). "The role of tissue eosinophils and their relationship with interleukin-5 in gastrointestinal disorders have not been elucidated." (PMID 40475764, 2025).
infectious disease (3 papers, 2021 to 2025). A disorder directly resulting from the presence and activity of a microbial, viral, or parasitic agent in humans. "Th2 lineage cells are believed to have developed to strengthen the removal of infectious diseases and are distinguished by the development of IL-4, IL-13, and Interleukin-5 (IL-5)." (PMID 35093033, 2022). "ARG1 is expressed by macrophages, and downregulates immunosuppressive cytokine production (e.g., IL-4, IL-5, and IL-13) by T-helper cell 2 (Th2) in response to infectious disease." (PMID 35008799, 2021). "Furthermore, they are also involved in immune response pathways (IL-5, IL-3, IL-2 signaling pathways, and B cell receptor signaling) and in controlling G1/S cell cycle, DNA damage response, and infectious diseases." (PMID 40287690, 2025).
intestinal disease (3 papers, 2013 to 2025). "In summary, our MR analysis has provided genetic evidence supporting the causal effects of multiple inflammatory factors – such as CCL19, CD40L, CCL20, PD-L1, IL-5, and M-CSF – on 5 distinct intestinal diseases (IBD, UC, CD, CAC, and CRC)." (PMID 41239614, 2025).
metabolic disease (3 papers, 2024 to 2025). A congenital disorder (due to inherited enzyme abnormality) or acquired (due to failure of a metabolically important organ) disorder resulting from an abnormal metabolic process. "The results showed that decreased metabolic disorder in recipient mice was accompanied by a significant elevation of Th2-type cytokines, including IL-4, IL-5, IL-6, IL-10, and IL-13." (PMID 38195424, 2024).
hematologic cancer (2 papers, 2021 to 2022). "The Severe-Death hematologic cancer group also had elevated concentrations of IL-5 and IL-13." (PMID 36700209, 2022). "Most of the drugs predicted using the DGIDb database are used in hematological cancers and disorders, in line with the findings of the MCODE enrichment analysis, showing the crucial role of platelet degranulation and Interleukin-3, Interleukin-5, and GM-CSF signaling." (PMID 33918694, 2021).
gastrointestinal disease (1 paper, 2022). A disease that occurs in the gastrointestinal system, excluding the hepatobiliary system. "IL-5 is involved in eosinophil differentiation and proliferation in bone marrow and prolonged survival and activation in the tissues, and its role in gastrointestinal diseases is becoming clearer." (PMID 39132061, 2022).
gastrointestinal tumor (1 paper, 2023). "Importantly, we noted that recombinant IL-5 administration is also related with inhibition of gastrointestinal tumor growth." (PMID 36376448, 2023).
vascular disorder (1 paper, 2018). A general term used to describe any disease affecting blood vessels]. "As IL-5 levels were dramatically elevated on both courses investigated, we explored a possible relationship of this cytokine and the other analytes implicated with vascular disorders for associations with clinically significant (≥grade 3) hypotension, or any grade capillary leak." (PMID 29967609, 2018).
IL5 also shares sentences with these, for which no sentence is quoted: lung (14 papers); chronic rhinosinusitis with nasal polyps (7); kidney diseases (4); cardiac disease (3); Hodgkins lymphoma (3); Hypercholesterolemia (3); hyperreactivity (3); lymph node metastasis (3); multiple myeloma (3); pharyngitis (3); adenocarcinoma (2); aneurysm (2); anterior uveitis (2); autism spectrum disorder (2); autoimmune thyroid disease (2); basophilic leukemia (2); Chagas disease (2); chronic periodontitis (2); dementia (2); endotoxemia (2); Henoch-Schönlein purpura (2); juvenile arthritis (2); Kimura disease (2); loiasis (2); Lymphadenopathy (2); microcephaly (2); neurodevelopmental disorder (2); neurological diseases (2); neuropathy (2); otitis media (2).
A further 167 diseases each share a sentence with IL5 in 2 papers or fewer.